ZNF716 (zinc finger protein 716)
Description:
May be involved in transcriptional regulation.
Synonyms: FLJ46189
Tractability: PROTAC: ubiquitination databases record sites on it.
Gene: Protein-coding gene on chromosome 7 (57,450,177 to 57,473,559, forward strand). Ensembl gene ENSG00000182111.
Subcellular location: Nucleus
Pathways (Reactome):
Gene expression (Transcription): Generic Transcription Pathway
Gene Ontology:
Molecular function: DNA-binding transcription factor activity, RNA polymerase II-specific; RNA polymerase II cis-regulatory region sequence-specific DNA binding
Biological process: regulation of DNA-templated transcription; regulation of transcription by RNA polymerase II
Cellular component: nucleus
Genetic constraint (gnomAD): Loss-of-function variants: 11 observed, 13.49 expected, observed/expected ratio (o/e) 0.82, 90% interval 0.51 to 1.35. The upper end of that interval is the gene's LOEUF score, 1.35, which puts it in group 5 of 6, group 1 being the genes least tolerant of losing a copy. Missense variants: 581 observed, 574.46 expected, observed/expected ratio (o/e) 1.01, 90% interval 0.94 to 1.08. Synonymous variants: 186 observed, 200.9 expected, observed/expected ratio (o/e) 0.93, 90% interval 0.82 to 1.05.
Homologues: Orthologues: chimpanzee ZNF716 (98% identical). Paralogues in human: ZNF254 (69% identical), ZNF708 (68% identical), ZNF679 (68% identical), ZNF726 (67% identical), ZNF728 (67% identical), ZNF735 (67% identical), ZNF492 (63% identical), ZNF90 (63% identical), ZNF722 (63% identical), ZNF676 (62% identical), ZNF714 (62% identical), ZNF486 (59% identical), and 164 more.
Diseases named in the same sentence as ZNF716 in open-access papers:
ZNF716 is named in the same sentence as 4 diseases in open-access papers, as found by Europe PMC text mining. Sharing a sentence is not in itself a finding about the gene and the disease. The quoted sentences say what the papers report.
cancer (1 paper, 2018). A tumor composed of atypical neoplastic, often pleomorphic cells that invade other tissues. "These CNV regions encode nineteen known genes, and some of which have been shown to affect aging-related phenotypes such as the shortening of telomere length (ZNF208), the risk of cancer (FOXA1, LAMA5, ZNF716), and vascular and immune-related diseases (ARHGEF10, TOR2A, SH2D3C)." (PMID 29883365, 2018).
ZNF716 also shares sentences with these, for which no sentence is quoted: Insulin resistance (1 paper); Obesity (1); type 2 diabetes (1).